NF1 (neurofibromin 1)
Diseases named in the same sentence as NF1 in open-access papers (continued):
Sharing a sentence is not in itself a finding about the gene and the disease.
ovarian carcinoma (57 papers, 2013 to 2026). A malignant neoplasm originating from the surface ovarian epithelium. "Together, these findings indicate that NF1 loss defines a DNA damage-associated mutational and cellular state in ovarian cancer." (PMID 42158468, 2026). "Here, we integrated cohort-scale somatic mutation profiling with functional validation to characterize the mutational and cellular consequences of NF1 loss in ovarian cancer." (PMID 42158468, 2026). "Loss-of-function of NF1 is common in epithelial ovarian cancer with a prevalence of 12–31%13,20,22,58,84,85." (PMID 41255967, 2025). "Another recent clinical study revealed that low expression of NF1 is associated with more extensive lymph node metastases and poor prognosis in epithelial ovarian cancer patients." (PMID 33061844, 2020). "They further confirmed that NF1 loss inhibited cisplatin-induced apoptosis and resulted in resistance to chemotherapy in ovarian cancer cells." (PMID 33061844, 2020). "In the GBM data, the involved pathways include parts of the RB signaling and RTK signaling pathways (CDKN2B, CDK4; EGFR, NF1 ), and in the ovarian carcinoma data a recurrent mutated module related to cell cycle and DNA repair (CCNE1, MYC, RAD52 ) is revealed." (PMID 24565034, 2013). "Somatic mutation data from the TCGA ovarian cancer cohort were analyzed to define NF1-associated mutation types, tumor mutational burden, mutational signatures, and co-occurring alterations in DNA damage repair (DDR) pathways, together with pathway- and gene set-level functional enrichment analyses." (PMID 42158468, 2026). "Furthermore, reduced tumor NF1 mRNA expression has been linked to poor prognosis in other cancer types, including hepatocellular carcinoma, ovarian cancer, and colorectal cancer." (PMID 41155378, 2025). "Analysis of larger series is necessary to distinguish whether ovarian cancer screening would be associated with benefits among women with NF1." (PMID 33734413, 2021). "Neurofibromin 1 (NF1) is a tumor suppressor gene frequently altered across diverse cancer types, yet its biological significance in ovarian cancer remains incompletely characterized." (PMID 42158468, 2026). "Ovarian cancer cells resistant to saracatinib display activation of the MAPK pathway via reduced NF1 expression or overexpression of HER2 and the insulin receptor." (PMID 34856074, 2022). "Another interesting result is our finding in ovarian cancer of a region affected in 25% of the cohort where our method points to NF1 as a potential driver." (PMID 36163358, 2022). "Our study found an increased prevalence and decreased age at diagnosis of ovarian carcinoma among patients with NF1 compared with the general population." (PMID 33734413, 2021). "Similar to NF1, breast cancer 1 (BRCA1) and BRCA2 mutations are associated with an increased lifetime risk of developing cancer--particularly breast and ovarian carcinoma." (PMID 33954070, 2021). "NF1 is also somatically altered in multiple sporadic tumors, including skin, lung, breast, and ovarian cancers, where its tumor-suppressive function seems to be linked primarily to Ras inhibition." (PMID 33096593, 2020).
ovarian carcinoma (continued). "Here, we have demonstrated that reduction in the expression of NF1 in two ovarian cancer cell lines results in activated MEK and ERK signalling, and is associated with decreased sensitivity to SRC inhibition." (PMID 29435137, 2018). "Knockdown of NF1 in two ovarian cancer cell lines resulted in resistance to AZD0530, and was accompanied with activated MEK and ERK signalling." (PMID 29435137, 2018). "Intriguingly, such mutations resulting in heterozygous or homozygous loss of NF1 expression are found to occur more often as sporadic events in AML and ovarian carcinoma, based on cBioPortal data." (PMID 28637487, 2017). "Our method is able to identify the known cancer drivers and further nominate candidates that exhibit higher breakpoint proximity than expected by random chance, such as DMD and LRRN3 in esophageal cancer, NF1 in ovarian cancer, CDK12 in uterine cancer, and WWOX in colorectal cancer." (PMID 36163358, 2022). "Most patients with NF1 and ovarian cancer had developed peritoneal and distant metastasis by last follow-up, which may be associated with the high mortality rate observed." (PMID 33734413, 2021). "This difference in mutational status explains the difference in KRAS community scores between pancreatic and ovarian cancers more accurately than cell lineage and stands in contrast to the NF1 gene community example where both a specific lineage and mutational status were important characteristics." (PMID 30573688, 2018). "NF1 was therefore selected for further investigation in two ovarian cancer cell lines." (PMID 29435137, 2018). "Importantly, it has been reported that NF1 is the fourth most altered gene in epithelial ovarian cancer, highlighting the relevance of this genetic alteration when targeting SRC in this disease setting." (PMID 29435137, 2018). "The Australian Ovarian Cancer Study (AOCS) specifically examined CNAs and reported regions of copy number loss at the NF1 locus in 34% (137/398) of ovarian cancer samples, comprising 157 serous adenocarcinomas from the TCGA cohort and a further 241 samples, of both endometrioid and serous subtypes." (PMID 28637487, 2017). "This led to the discovery that 6 out of 18 ovarian carcinoma-derived cell lines had markedly reduced or lacked expression of NF1 protein, with 5 of the 6 cell lines harbouring NF1 mutations." (PMID 25026295, 2014). "Qiao et al10 reported that the NF1 overexpression induced autophagy and inhibited mTOR/P70S6K signalling in ovarian carcinoma cells and in turn inhibited ovarian carcinoma cell proliferation and invasion." (PMID 32862562, 2020). "For example, CDKN2B and CDK4 as well as EGFR and NF1 are involved in the RB and RTK signaling pathways, respectively and the CCNE1, MYC and RAD52 module in ovarian carcinoma is involved in cell cycle." (PMID 24565034, 2013). "Stable NF1 knockdown ovarian cancer models showed that NF1 depletion did not affect basal proliferation but increased sensitivity to hydroxyurea-induced replication stress, accompanied by increased γH2AX accumulation." (PMID 42158468, 2026). "The mutation frequencies for NF1, RB1, and KIT in our BM samples were not in the range described for ovarian cancer specimens, they were less frequent." (PMID 28497333, 2017).
tuberous sclerosis (54 papers, 2010 to 2025). Hereditary disease characterized by seizures, intellectual disability, developmental delay, and skin and ocular lesions. "Certain hereditary syndromes, such as Neurofibromatosis type I (NF-1) and Tuberous Sclerosis complex (TSC), are associated with LGG." (PMID 34828788, 2021). "Nevertheless, important insights about underlying neurobiology of ASD has been gained through the study of single-gene disorders like Fragile X (FXS), tuberous sclerosis (TS), and neurofibromatosis 1 (NF1) which are associated with a high penetrance of ASD." (PMID 33519543, 2020). "Half the studies excluded patients with low-grade tumour predisposition syndromes such as NF1 and tuberous sclerosis." (PMID 29948767, 2018). "Neurofibromatosis type 1 (NF-1) and tuberous sclerosis (TS) are autosomal dominant tumor susceptibility syndromes caused by inactivating mutations in the tumor suppressor genes NF1 and TSC1 and TSC2, respectively." (PMID 25092520, 2014). "Lastly, retinal astrocytic hamartomas can calcify but are well circumscribed, lack hemorrhage or necrosis, and are associated with other findings related to tuberous sclerosis (TS) or neurofibromatosis 1 (NF1)." (PMID 23577029, 2013). "Specifically, von Hippel-Lindau disease (VHL), neurofibromatosis type 1 (NF-1) and possibly tuberous sclerosis (TSC) are associated with endocrine neoplasms." (PMID 24281208, 2010). "Roughly 10% of cases are related to familial endocrine tumor syndromes and include multiple endocrine neoplasia type 1 (MEN1), von-Hippel Lindau disease (VHL), neurofibromatosis type 1 (NF-1), and tuberous sclerosis (TSC)." (PMID 37568572, 2023). "Genetic associations are also seen in Von-Hippel Lindau (VHL) disease, neurofibromatosis type 1 (NF-1), and tuberous sclerosis complex (TSC)." (PMID 36507125, 2022). "Comparable to the NF1 pre-cNF, hamartia are microscopic lesions well-documented in the Tuberous Sclerosis Complex that precede and evolve into hamartomas." (PMID 31107888, 2019). "For instance, mutations in PTEN, neurofibromatosis (NF1) or in the tuberous sclerosis complex, cause an overactivation of the PI3K/Akt/mTOR pathway, leading to autism-related behavior, tuberous sclerosis and macrocephaly." (PMID 26877878, 2016). "Finally, in NEN associated with MEN2, NF1, VHL, and tuberous sclerosis data on the efficacy of SSAs are scarce and derive generally from case reports." (PMID 37581846, 2024). "Although mostly sporadic, PanNET can develop as a component of hereditary multi-tumor syndromes, including multiple endocrine neoplasia type 1 (MEN1), von Hippel-Lindau (VHL) disease, and, more rarely, neurofibromatosis type 1 (NF-1), and tuberous sclerosis (TSC)." (PMID 36428573, 2022). "Several monogenic autism spectrum disorders have mutations leading to defects in the PI3K pathway, such as tuberous sclerosis (TS), fragile X syndrome (FXS), neurofibromatosis 1 (NF1), and brain disorders associated with phosphatase and tensin homolog (PTEN) mutations." (PMID 26770665, 2016). "Certain genetic syndromes, including Carney complex, neurofibromatosis types 1 and 2 (NF1 and NF2), and tuberous sclerosis complex (TSC), are associated with the development of both cardiac and cerebral tumors." (PMID 40427120, 2025). "These lesions are most commonly sporadic but can also be a part of genetic syndromes such as Multiple Endocrine Neoplasia 1 (MEN1), Von Hippel-Lindau disease VHL, Neurofibromatosis1 (NF-1), and Tuberous Sclerosis (TSC)." (PMID 38672582, 2024). "Genetic syndromes with high ASD prevalence rates include Fragile X Syndrome (FXS), Angelman syndrome (AS), Tuberous Sclerosis Complex (TSC) and Neurofibromatosis type 1 (NF1)." (PMID 35651825, 2022). "Hereditary syndromes associated with PNETs are Multiple Endocrine Neoplasia type 1 (MEN1), Von Hippel–Lindau disease (VHL), Neurofibromatosis type 1 (NF1), and Tuberous Sclerosis Complex (TSC)." (PMID 34122352, 2021).
tuberous sclerosis (continued). "Neurofibromatosis type 1 (NF1) and Neurofibromatosis type 2 (NF2), tuberous sclerosis complex (TSC), von Hippel–Lindau disease (VHL), Sturge–Weber syndrome (SWS), and ataxia–telangiectasia (A-T) exemplify this group." (PMID 40558831, 2025). "These syndromes are caused by mutations in genes variably linked to the PI3K/Akt/mTOR pathway, such as Multiple Endocrine Neoplasia-1 (MEN1), Neurofibromatosis-1 (NF1), Tuberous sclerosis (TSC1/2), Von Hippel-Lindau (VHL) and Cowden syndrome (PTEN)." (PMID 29509701, 2018). "Similarly, analysis of Nf1−/− and Tsc2+/− mice has suggested treatments to correct behavioral impairment in neurofibromatosis and tuberous sclerosis complex (TSC)." (PMID 22558107, 2012). "Activation of the PI3K‐AKT pathway in classical NF1 may therefore account for tumour formation, as the pathway is activated in other tumour forming syndromes: neurofibromatosis 2, Cowden, CLOVES and tuberous sclerosis." (PMID 39355740, 2024).
schwannoma (48 papers, 2009 to 2026). A benign, usually encapsulated slow growing tumor composed of Schwann cells. "While schwannomas are more commonly associated with NF-2, these can be seldom encountered with NF-1." (PMID 40416267, 2025). "Clinicians should reconsider the indications for surgery in cases of schwannomas associated with NF-1 that are discontinued before medical treatment." (PMID 40861330, 2025). "Loss of SMARCB1 was also related to Schwannoma, another phenotype found in NF1 despite being more frequent in NF2." (PMID 32858845, 2020). "Café-au-lait macules and neurofibromas are hallmark features of NF1, whereas NF2 is primarily characterized by schwannomas, meningiomas, and ependymomas; NF3 is characterized by multiple schwannomas typically sparing the vestibular nerves." (PMID 41515658, 2026). "Schwannomas, while less common in NF-1 than NF-2, do sometimes occur in NF-1 patients, most commonly along the cranial, spinal, or peripheral nerves." (PMID 40416267, 2025). "Nerve sheath tumors such as NF and Schwannoma are common, with the disease prevalence being 1:3500 for NF1 and 1:50,000 for NF2." (PMID 39857711, 2025). "Schwannoma must be considered in the differential for any rectal mass discovered in a patient with NF-1, so that the patient can be appropriately managed and treated." (PMID 40416267, 2025). "The overlapped markers and pathways in both schwannomas and NF1-related tumors underscore shared vulnerabilities that can be therapeutically exploited." (PMID 39518076, 2024). "Plexiform lesions in patients with NF2 are typically revealed to represent plexiform schwannomas, in contrast to the plexiform neurofibromas of NF1." (PMID 31161239, 2020). "Schwannoma in NF-1: a pitfall for detecting malignancy by metabolic imaging." (PMID 38013269, 2023). "In addition, studies showed identical or only modestly elevated RAS-GTP levels in NF1-deficient human neuroblastoma cells, in contrast to highly elevated RAS-GTP levels in NF1-deficient Schwannoma tumor cells." (PMID 27130733, 2016). "The transcription factor target analysis using the WebGestalt tool showed that this gene was enriched, suggesting that schwannomas may also be related to NF1 deregulation." (PMID 23354516, 2013). "NF2, in contrast to neurofibromatosis type 1 (NF1) is characterised by the development of schwannomas, meningiomas and ependymomas, with the great majority of patients developing bilateral schwannoma involvement of the superior vestibular branch of the eighth cranial nerve." (PMID 19545378, 2009). "Finally, our studies using Nf1 deletion to activate the MAPK pathway suggested that this signaling pathway might modify schwannoma development." (PMID 32960816, 2020). "They include schwannomas, neurofibromas, and MPNST, the latter of which can be life-threatening in patients with NF-1." (PMID 40861330, 2025). "The present case was rare and exceptional in that it did not occur against a background of NF1, had weak malignancy, and had a schwannoma-like component in the surrounding tissue." (PMID 39516973, 2023). "The incidence of schwannoma in patients with NF-1 is unknown, and there are no sex-related differences in the incidence." (PMID 40861330, 2025). "The NF1 mechanism is distinct from that in NF2 involving the mutation of NF2, which encodes the ezrin-radixin related protein, merlin, resulting in the development of true schwannomas rather than cNF or pNFs." (PMID 31107888, 2019).
leukemia (47 papers, 1994 to 2025). A malignant (clonal) hematologic disorder, involving hematopoietic stem cells and characterized by the presence of primitive or atypical myeloid or lymphoid cells in the bone marrow and the blood. "There was also an increased risk of childhood leukemias among individuals with NF1 (aHR, 4.1; 95% CI, 1.7-9.8)." (PMID 37490289, 2023). "On the other hand, Nf1 heterozygous deletion in embryonic stem cells predisposes mice to develop various tumors including leukemia." (PMID 34944812, 2021). "Other pathologies such as cardiovascular abnormalities, learning deficiencies, and a variety of malignancies such as rhabdomyosarcoma, leukemia, and gastrointestinal stromal tumor can also be associated with NF1." (PMID 28622765, 2017). "Hydroquinone also increases proliferation of CFU-GM progenitor cells in mice with Nf1 null bone marrow relative to WT, the same cell type associated with benzene-associated leukemia." (PMID 24386979, 2014). "Increased Ras signaling is implicated as a causal factor in the increased pre-disposition to leukemia of individuals with mutations in NF1." (PMID 24386979, 2014). "The recurrently deleted region on 17q overlaps with NF1, which is correlated with increased risk of pediatric leukemia." (PMID 23533652, 2013). "A recent study suggested that NF1 may be associated with leukemia, particularly juvenile myelomonocytic leukemia, which has been reported in connection with NF1, indicating the need for more detailed investigations." (PMID 41001300, 2025). "In the present case, the possibility that an NF1 abnormality caused the leukemia is merely a speculation." (PMID 41001300, 2025). "A modestly increased leukemia risk was observed only among children with NF1." (PMID 37490289, 2023). "Leukemia risk was increased only among children with NF1 (HR, 4.1; 95% CI, 1.7-9.8)." (PMID 37490289, 2023). "Similarly, in leukemias, NF1 loss in patient or murine hematopoietic precursors, results in increased RAS-MEK/ERK pathway activation." (PMID 35188187, 2022). "The loss of ASXL1 or p19ARF can accelerate the development of leukemia in the haploinsufficient Nf1 mouse model, which may be due to the promoter methylation or activation of the MYC and MAPK pathway, respectively." (PMID 34566848, 2021). "The association between leukemia and NF1 is controversial and needs to be further investigated." (PMID 34566848, 2021). "Recurrent copy number alterations (CNAs) were identified in genes related to leukemia and hematopoiesis, among which deletions of a region containing NF1, EVI2A and EVI12B were particularly frequent (n = 6)." (PMID 38972954, 2024). "These included CDH1-Blepharocheilodontic (BCD) Syndrome, CHEK2-osteosarcoma, NF1-leukemia, and NF1-pulmonary stenosis." (PMID 33959510, 2021). "NF1 encodes neurofibromin, a GTPase-activating protein and a known repressor of RAS; thus, loss of one copy of NF1 due to germline mutation and subsequent loss of the second NF1 allele in JMML result in RAS hyperactivity in leukemia cells." (PMID 35054439, 2021). "Our AML cohort was characterized by mutations in genes with a known pathogenic role in leukemia and the identified chimeras contributed to the disease complexity, as demonstrated by the involvement of genes such as WT1 or copy-number loss of NF1." (PMID 31817495, 2019). "To further investigate the possible role of Nf1 in development of hematological malignancies such as leukemia following exposure to HQ, we measured the proliferative ability of myeloid hematopoietic progenitor cells after treatment." (PMID 24386979, 2014). "NF1 has been recently identified as important in the development of acute myelogenous leukemia (AML), the same form of leukemia that is associated with exposure to benzene, an established human leukemogen." (PMID 24386979, 2014).